SOX2 (SRY-box transcription factor 2)
Diseases named in the same sentence as SOX2 in open-access papers (continued):
Sharing a sentence is not in itself a finding about the gene and the disease.
lung carcinoma (continued). "The siRNA-mediated knockdown of SOX2 in D121 lung carcinoma cells, which led to the decisive inhibition of these cells' migration in a transwell migration assay suggests that this transcription factor may regulate key biological functions of these cells." (PMID 21468047, 2011). "Furthermore, increased expression of SOX2 may serve as a prognostic indicator for individuals undergoing surgical intervention at stages I and II of lung cancer." (PMID 39976818, 2025). "In addition, SOX2 interacts with CDK1 to promote lung cancer cell stemness." (PMID 38164286, 2024). "Furthermore, the hub genes SOX2 and PITX2 have been associated with lung cancer and smoking." (PMID 39595659, 2024). "Moreover, it was reported that SOX2 confers resistance to ferroptosis through upregulation of SLC7A11 expression in lung cancer stem-like cells (CSLC) which implies that SOX2 could be a potential therapeutic target for cancer treatment." (PMID 36926345, 2023). "However, further studies are required to identify the potential treatment effects of SOR on SOX-2 and its inflammation-related genes in lung cancer progenitor cells will provide further insights into the pathology and new therapeutic avenues for more effective treatment of lung cancer." (PMID 37259369, 2023). "Notably, SOX2 overexpression decreases cisplatin-induced cell apoptosis in lung cancer, while inhibition of SOX2 enhances cisplatin toxicity and promotes apoptosis in A549 and A549/CDDP cells, suggesting that SOX2 is a vital regulator of cisplatin resistance in NSCLC." (PMID 35059870, 2022). "Thus, further studies should be conducted to explore whether other molecules affect SOX2 in cisplatin-resistant lung cancer cells." (PMID 35059870, 2022). "Moreover, the depletion of SOX2 contributes to notable cell apoptosis in lung cancer." (PMID 34521353, 2021). "Therefore, HEBR protein may be combined with cancer drugs to suppress the Sox-2 and Oct-4 gene expression of lung cancer stem cells." (PMID 34885925, 2021). "Also, downregulation of SOX2 was found to suppress growth and metastasis of lung cancer." (PMID 33489519, 2020). "Silencing SOX2 in TICs could suppress growth and metastasis of lung cancers." (PMID 30517668, 2020). "Additionally, high expression of c-Myc could maintain cancer stemness by increasing the transcriptional activity of SOX2 in lung cancer cells." (PMID 33153498, 2020). "In non-smokers exposed to air pollution, SOX2 promoter methylation might help in the early prediction of lung cancer risk." (PMID 30867047, 2019). "Moreover, recent studies using in vitro and in vivo assays of neural stem cell and human lung cancer cell survival have demonstrated that silencing of Sox2 results in decreased levels of survivin, a member of the inhibitor of apoptosis protein family, and induced apoptosis." (PMID 29352015, 2018). "Our observation that a stemness marker SOX2 was upregulated in lung cancer tissues concurrently with the reduced level of activated p38, prompted us to investigate a possibility that p38 may inhibit stemness by downregulating the stemness proteins in lung cancer cells." (PMID 28460458, 2017).
lung carcinoma (continued). "Recently, accumulating evidence demonstrated that SOX2 expression level is closely correlated with clinical progression and poor prognosis among various tumor types, including hepatocellular carcinoma, colorectal cancer, lung cancer, gastric cancer, and laryngeal squamous cell carcinoma." (PMID 24828201, 2014). "Interestingly, a recent study reported that the downregulation miR-638 can promote CRC cell invasion and EMT though inhibiting SOX2, a target of miR-638 reported in lung cancer, confirming that miR-638 exerts important function in CRC by regulation different targets." (PMID 25301729, 2014). "In addition, SOX2 overexpression has been shown to be essential for lung cancer stem cell function." (PMID 24940116, 2014). "In addition, this finding also supported the contribution of SOX2 to the tumorigenesis capacity of lung cancer cells since it was well established that the SP has higher tumorigenesis property than NSP in various types of lung cancer cells." (PMID 22615765, 2012). "As a result, this stabilizes several oncogenic drivers including SOX2, MYC and SMAD7 in lung cancer." (PMID 39806421, 2025). "High levels of BCAT1 promote the expression of SRY-box 2 (SOX2) by reducing alpha-ketoglutarate (α-KG), leading to the migration and metastasis of lung cancer cells." (PMID 40438606, 2025). "According to western blot and immunofluorescence analyses, SM-3-treated human lung cancer cells (A549, H292, and H460) showed decreased levels of stem cell markers (CD44, CD133, ALDH1 A1) and stem cell transcription factors (NANOG, OCT4, SOX2)." (PMID 40287470, 2025). "For instance, in lung cancer, ALKBH5 counteracts YTHDF2-mediated degradation of Sox2 and thereby promoting tumor aggressiveness." (PMID 39098905, 2024). "The expression of SOX2 and SOX9 is mutually exclusive and is regulated under epigenetic control, influencing tumor growth and invasion in lung cancer." (PMID 39372390, 2024). "SLC7A11 can be activated by the transcriptional factor SRY-box transcription factor 2 (SOX2) and the splicing factor 3b subunit 1 (SF3B1) in lung cancer cells." (PMID 39624080, 2024). "We aimed to cross-validate these findings on human and murine lung cancer cells and observed that CD133 + CSC differentially expressed higher levels of HA, HAS3, ABCC5, SOX2, and CD47 (p < 0.01)." (PMID 39039104, 2024). "Further mechanistic exploration revealed that lung cancer stem-like cells (CSLCs) resist ferroptosis by upregulating the cystine transporter SLC7A11, activated by the stem cell transcription factor SOX2." (PMID 39944353, 2024). "Another study with lung cancer cells, demonstrated the involvement of TGF-β signaling in downregulation of SOX2 inducing EMT and promoting a change in cell morphology accomplished by a resistance to treatment." (PMID 38275880, 2024). "FGFR1-amplification in lung cancer cell lines H1581 and DMS1144 was shown to promote EMT, migration, and invasion, which were attributed to SOX2 expression." (PMID 38612911, 2024). "A previous study has additionally documented the significance of stem cell transcription factors, including Oct4, Sox2, Nanog, and KIF4, in the progression of lung cancer." (PMID 38438773, 2024). "This phenomenon was related to the interaction between SOX2 and TGF-β, which reduced the expression level of SOX2 to induce EMT and promote metastasis of lung cancer cells." (PMID 39175042, 2024). "In lung cancer stem-like cells, SRY (sex determining region Y)-box 2 (SOX2) binds to the SLC7A11 promoter to increase its expression, conferring ferroptosis resistance and promoting stemness." (PMID 38705513, 2024). "In lung cancer, the PCAT1/SOX2 axis promotes tumorigenesis and immunosuppression by inhibiting cGAS/STING-signaling-mediated T cell activation." (PMID 38164286, 2024).
lung carcinoma (continued). "The overexpression of SOX2 resulted in increased proliferation, EMT signature, migration, and invasion of lung cancer cells." (PMID 38612911, 2024). "A recent study revealed that sex-determining region Y-box 2 (SOX2) promotes LC3A expression and enhances the proliferation of lung cancer cells." (PMID 38431606, 2024). "AZD4547 is a FGFR1 inhibitor that markedly suppressed SOX2 expression and tumor growth in orthotopic and subcutaneous H1581 and DMS1144 lung cancer xenograft models." (PMID 38612911, 2024). "They identified EP300 as a key mediator of SOX2 expression, and CBP30, which is an EP300 inhibitor, reduced MGH7 and ChaGoK1 lung cancer cell growth in vitro." (PMID 38612911, 2024). "We performed data mining using the University of California Santa Cruz genome browser and Gene Expression Database of Normal and Tumor Tissues 2 (GENT2) and confirmed overexpression of SMO, GLI1, SOX2, and SOX2OT in lung cancer samples." (PMID 37149646, 2023). "In our research, lung cancer cells treated with DH_32 exhibited a reduction in the mRNA expression levels of the OCT4, NANOG, and SOX2 transcription factors." (PMID 38132948, 2023). "Accumulated GLI1 activated SOX2/SOX2OT transcription by interacting with their promoter, ensuring positive self-regulation and consistent activation of the GLI1-SOX2OT loop in lung cancer cells." (PMID 37149646, 2023). "The major stem cell markers for lung cancer include surface biomarkers, such as CD44, CD133, and integrin α6, and intracellular biomarkers, such as ALDH1, Nanog, Oct4, and Sox2." (PMID 37298389, 2023). "To understand how dinactin inhibits CSCs properties in the lung cancer cells, we next investigated expression of genes of the well-known lung CSC markers, including ALDH1A1, Nanog, CD133, Oct4, and Sox2 genes by qRT-PCR." (PMID 36551502, 2022). "In conclusion, our study suggested that TRIB3 links integrin αvβ3 signals to induce lung cancer progression, which was coordinated with AKT/SOX2 signals." (PMID 35473511, 2022). "In the lung cancer group, CYFRA21‐1 had a significant difference in age and sex, and SOX2, MAGE A1, CYFRA21‐1, NSE, and SCCA were significantly different in pathological type and TNM." (PMID 35596744, 2022). "The stemness markers of lung cancer stem cells mainly include ALDH1, ABCG2, CD44, CD133, NANOG, and SRY-box transcription factor 2 (SOX2)." (PMID 36338714, 2022).
lung carcinoma (continued). "Previously, we reported that enhanced O-GlcNAcylation is important for SOX2 expression and maintenance of CSC properties, including sphere- and tumour-forming activities, in colon and lung cancer cells." (PMID 35190631, 2022). "Our SOX2 and ALDH1 results contrast with those obtained using Δ and OE MSLN models from lung cancer cell lines." (PMID 35162954, 2022). "Tumors with higher SOX2 expression are more resistant to ferroptosis, and the expression of SLC7A11 is positively correlated with SOX2 in mouse and human lung cancer tissues." (PMID 36105219, 2022). "In lung cancers, different CSC populations have been identified according to the expression of some markers, such as CD44, CD90, CD117, EGF, Axl, and Sox2, in different combinations." (PMID 36555420, 2022). "Another supporting study showed that TRPM7 overexpression resulted in the increased expression of cancer stemness markers such as SOX2, KLF4, and CD133 in lung cancer, while TRPM7-silencing led to the reduction of stemness and EMT traits." (PMID 35771152, 2022). "In lung cancer cell lines (H1581 and DMS114), FGF2-dependent activation of the FGFR1/ERKs pathway led to upregulation of SOX2 (Sry-related HMG box 2), which in turn promoted EMT and cell migration." (PMID 34830951, 2021). "In the study of lung cancer, it was found that when ENPP1 gene was knocked out in lung cancer cell lines, the expression of a large number of stem cell markers decreased, including ABCG2, SOX2, NANOG, and CD44." (PMID 33635867, 2021). "Other pathways that are involved in CAF-induced resistance of lung cancer cells to chemotherapy include the ANXA3/JNK, IGF2/AKT/Sox2/PG-P, and PI3K/Akt/GRP78 signaling pathways." (PMID 33673405, 2021). "Accumulating evidence presents the reduction of Oct4, Sox2, and Nanog expression levels as an effective strategy to suppress CSC characteristics in lung cancer." (PMID 34349823, 2021). "To explore a possible causal relationship between overexpression of BCAT1 and increased SOX2 expression in metastatic lung cancer cells, we knocked down BCAT1 in these cells and observed consequent reduction of SOX2 at both the mRNA and protein level." (PMID 34646394, 2021). "We found that high expression of BCAT1 negatively regulates miR200c expression in metastatic lung cancer cells, suggesting a possible post-transcriptional influence of BCAT1 on SOX2 expression." (PMID 34646394, 2021). "In the current study, the gene expression of Sox-2 and Oct-4 decreased the HEBR-treated lung cancer cells, especially for H1299 cells." (PMID 34885925, 2021). "Immunohistochemically assessed cell positivity for ALDH1A1, SOX2, NANOG, OCT-4, and c-MYC, which are considered as lung cancer stem-like cells markers." (PMID 32500024, 2020). "Silencing of USP4 significantly reduced Oct4 and Sox2 protein expression, suggesting that silencing of USP4 can inhibit lung cancer cell stemness." (PMID 32549341, 2020). "We demonstrated that ciclesonide had anti-proliferative properties against lung cancer and inhibited lung CSC formation through suppression of Hedgehog signaling and SOX2." (PMID 32033067, 2020).
lung carcinoma (continued). "In lung cancer, approximately 50% of a cohort of NSCLC patients elicited both CD4+ and CD8+ T-cell responses against SOX2 and the responses were readily detectable in the peripheral blood mononuclear cells." (PMID 30517668, 2020). "One of these genes, BCL2L1, is known to collaborate with SOX2 to promote cell proliferation in lung cancer; nuclear translocation of IGF1R induced growth arrest and apoptosis resistance of lung cancer cells." (PMID 30497474, 2018). "As2O3 was shown to inhibit the proliferation and reduce the tumor sphere formation of lung cancer cells as well as reduce the expression of stem cell biomarker CD133 and transcription factors such as Sox2 and Oct4." (PMID 30477221, 2018). "In this study, we established technologies to generate lung CSC-like cells from human lung cancer cell line A549 by introducing OCT3/4, SOX2 and KLF4, and to construct “lung cancer organoids” in vitro that mimicked human lung cancer tissues." (PMID 28951614, 2017). "MiR-410 elevated the expressions of stem cells markers such as Oct4, Sox2, Nanog, CXCR4 and putative lung cancer stem cells surface marker CD44 and CD166." (PMID 28076327, 2017). "Autoantibodies to SOX2 are considered to be mainly detected in small cell lung cancer (SCLC) The remaining antigens GBU4-5 and Annexin I are also expressed in lung cancer." (PMID 28750095, 2017). "We demonstrate miR-410 increases the levels of stem cells marker Sox2, Oct4, Nanog, CXCR4 as well as lung cancer stem cells surface marker CD44 and CD166." (PMID 28076327, 2017). "SOX2 has been identified as the driving gene of the 3q25-27 amplicon, which is common in most NSCLC cases and contributes to the pathogenesis of lung cancer by controlling cell proliferation and malignant transformation." (PMID 26780934, 2016). "Intriguingly, pterostilbene dose-dependently suppressed self-renewal ability in M2-TAMs-co-cultured lung cancer cells, and this suppression was accompanied by downregulation of MUC1, NF-κB, CD133, β-catenin, and Sox2 expression." (PMID 27276704, 2016). "Therefore, Sox2 may be considered as a potential target for the treatment of lung cancer." (PMID 27371094, 2016). "SOX2 has shown to increase CSC markers in ovarian, pancreatic, lung cancer, but research also has proven its function in self-renewal." (PMID 25114775, 2014). "Again, contrasting results for SOX2’s role in the clinic were highlighted in lung cancer (including NSCLC and SCLC), where SOX2 was correlated to improved survival and better patient outcome." (PMID 25114775, 2014). "Expression of stem cell related transcription factors OCT4, SOX2, SSEA1, and SSEA4 were analyzed on sections from the LC-42 and the other three lung cancer cell lines." (PMID 23738757, 2013). "In this regard, our results demonstrated that silencing of SOX2 significantly reduces the protein expression level of oncogenes-WNT1, WNT2, c-MYC and NOTCH1 in human lung cancer and further revealed other target cancer genes of SOX2." (PMID 22615765, 2012). "Our results thus far demonstrate that SOX2 regulates the transcriptional network of oncogenes, including WNT1, WNT2, NOTCH1 and c-MYC and promotes the tumorigenesis of human lung cancer cells." (PMID 22615765, 2012). "Therefore, SOX2 could possibly serve as a potential target for improved treatment of lung cancer." (PMID 21468047, 2011). "Moreover, lung cancer cells treated with SM-3 exhibited decreased mRNA expression levels of the transcription factors NANOG, OCT4, and SOX2." (PMID 40287470, 2025).